GBP2 (guanylate binding protein 2)
Diseases named in the same sentence as GBP2 in open-access papers (continued):
Sharing a sentence is not in itself a finding about the gene and the disease.
glioma (continued). "In glioma, GBP2 knockdown impairs proliferation and migration." (PMID 41181145, 2025). "For example, GBP2 accelerated the proliferation and migration of glioma via KIF22/EGFR pathway." (PMID 37622120, 2023). "Western blotting confirmed the high depletion efficiency of GBP2 in both glioma cell types." (PMID 35436989, 2022). "These integrated analyses suggest that GBP2 glioma is involved in immune regulation and might be a valuable immunotherapeutic target." (PMID 36186425, 2022). "We further examined the prognostic significance of GBP2 for glioma." (PMID 36186425, 2022). "Time-dependent ROC curves also demonstrated that GBP2 has predictive power in glioma prognosis." (PMID 36186425, 2022). "In this work, we identified GBP2/KIF22/EGFR as a potential therapeutic target for glioma." (PMID 35436989, 2022). "In particular, GBP2 showed the highest fold change in gliomas among other cancer types." (PMID 36186425, 2022). "We next explored the role of GBP2 in tumor immunity of glioma." (PMID 36186425, 2022). "In this work, we demonstrate that GBP2 has high expression levels in glioma tissues." (PMID 35436989, 2022). "In addition, GBP2 showed higher expressions in tumor tissue from glioma patients than in normal brain tissue in the Human Protein Atlas database." (PMID 36186425, 2022). "We investigated the clinical significance of GBP2 in glioma." (PMID 36186425, 2022). "In summary, we demonstrate that GBP2 was overexpressed in glioma tissues." (PMID 35436989, 2022). "We found GBP2 were increased in glioma tissues at both mRNA and protein levels." (PMID 36186425, 2022). "In this study, we examined the clinical relevance of GBP2 to glioma and explored the immune properties of GBP2 using single cell, immune infiltration and immunomodulatory analyses, and finally analyzed potential regulators of GBP2." (PMID 36186425, 2022). "The results demonstrated that GBP2 expression was elevated in glioma tissues." (PMID 36186425, 2022). "In brief, these data suggested that GBP2 played an important role in glioma immune microenvironment, and may be involved in immune regulation." (PMID 36186425, 2022). "We then explored the correlation of GBP2 expression with immune cells in gliomas." (PMID 36186425, 2022). "Furthermore, to confirm whether GBP2 promoted the glioma progression by KIF22, we overexpressed KIF22 in GBP2 knockdown cells." (PMID 35436989, 2022). "However, there are fewer studies on the immune properties of glioma related to GBP2." (PMID 36186425, 2022). "Our previously study showed that GBP2 could regulate the cell growth and migration of glioma cells." (PMID 36186425, 2022). "Therefore, we further investigated the role of GBP2 in gliomas." (PMID 36186425, 2022). "Besides, we also indicated that GBP2 played a critical role in glioma proliferation." (PMID 35436989, 2022). "Mechanistically, GBP2 directly interacts with kinesin family member 22 (KIF22) and regulates glioma progression through KIF22/epidermal growth factor receptor signaling in vitro and in vivo." (PMID 41181145, 2025). "We employed knockdown and overexpression strategies, and the results of in vitro and in vivo assays were highly consistent in demonstrating the function of GBP2 and KIF22 as oncogenes in glioma." (PMID 35436989, 2022). "Although studies have shown that guanylate-binding protein 2(GBP2) has critical roles in various cancers, its function in glioma is unclear." (PMID 35436989, 2022). "In summary, we clarified the oncogenic role of GBP2 in glioma and elucidated for the first time the GBP2/KIF22/EGFR pathway in glioma progression." (PMID 35436989, 2022). "Regarding the mechanism, we clarify that EGFR signaling was regulated by GBP2, and also demonstrated that GBP2 directly interacted with KIF22 and regulated glioma progression through KIF22/EGFR signaling." (PMID 35436989, 2022).
glioma (continued). "In KM analysis of WHO grades, we found that high GBP2 expression in WHO grades (G3 and G4) predicted worse survival, which indicated high expression of GBP2 also predicts poor survival outcomes in high-grade gliomas." (PMID 36186425, 2022). "Regarding the mechanism, we clarify that epidermal growth factor receptor (EGFR) signaling is regulated by GBP2, and also demonstrate that GBP2 interacts directly with kinesin family member 22(KIF22) and regulates glioma progression through KIF22/EGFR signaling in vitro and in vivo." (PMID 35436989, 2022). "Therefore, GBP2-involved non-coding network provide insights into the noncoding-mediated mechanisms in glioma prognosis and therapy." (PMID 36186425, 2022). "As the co-IP results indicated, GBP2 could interact with KIF22 in glioma cells, but not DDX31 and YTHDF2." (PMID 35436989, 2022). "Unlike GBP1, GBP2-promoted glioma cell invasion mainly through induction of FN121." (PMID 33608513, 2021).
Sepsis (6 papers, 2020 to 2025). Sepsis is defined as life-threatening organ dysfunction caused by a dysregulated host response to infection. "High mortality after low dose LPS challenge in Gate-16−/−Gabarap−/− mice primed with poly(I:C) or polymicrobial sepsis was ameliorated by compound GBP2 deficiency." (PMID 33042141, 2020). "In addition, GBP2 was closely associated with the activation of caspase-11 inflammasomes, hence facilitating the occurrence of sepsis." (PMID 37622120, 2023). "Our study demonstrates that GBP2 is highly expressed in macrophage-derived EVs during sepsis and in the peripheral blood mononuclear cells of sepsis patients." (PMID 40156957, 2025). "•During sepsis-induced acute lung injury, GBP2 is enriched in macrophage and macrophage-derived extracellular vesicles." (PMID 40156957, 2025). "Elevated GBP2 expression was observed in EVs and monocytes from the peripheral blood of sepsis patients, in LPS-stimulated THP-1 and RAW264.7 cells and their secreted EVs, and in macrophages within the lungs of CLP mice." (PMID 40156957, 2025). "Reanalysis of previously published scRNA-Seq data from sepsis patients (GSE167363) revealed that a higher proportion of monocytes expressed elevated levels of GBP2 in sepsis patients." (PMID 40156957, 2025). "The regulation of caspase-11 activation by GBP2 is itself modulated by GABA type A receptor-associated protein autophagy proteins, which negatively regulate GBP2-dependent inflammasome activation to protect against sepsis." (PMID 41181145, 2025). "Here we demonstrate that GABARAP autophagy proteins negatively regulate GBP2-dependent caspase-11 inflammasome activation to prevent sepsis." (PMID 33042141, 2020). "Taken together, these data demonstrate that GABARAP autophagy proteins specifically limit GBP2-dependent caspase-11 inflammasome activation and sepsis." (PMID 33042141, 2020). "Next we tested the physiological significance of Gate-16 and Gabarap for inhibition of GBP2-dependent caspase-11 inflammasome activation during polymicrobial sepsis in the CLP model." (PMID 33042141, 2020). "Similarly, GBP2 was highly expressed in the peripheral blood monocytes of sepsis patients and the lung tissue of CLP- or LPS-treated mice." (PMID 40156957, 2025). "The gene expression of GBP2, GBP6, and GBP7 in the Sham group was significantly higher than that in the sepsis group." (PMID 36405762, 2022). "Moreover, the expression of GBP2 in peripheral blood EVs is positively correlated with vascular barrier damage markers, D-dimer, and SOFA scores, both of which are established indicators of sepsis severity." (PMID 40156957, 2025).
esophageal squamous cell carcinoma (5 papers, 2017 to 2022). Esophageal squamous cell carcinoma (ESCC) is a type of esophageal carcinoma (EC) that can affect any part of the esophagus, but is usually located in the upper or middle third. "In esophageal squamous cell carcinoma, up-regulation of GBP2 and IRF-1 as its maintranscriptional regulator proposed it as a possible cancer-related marker (Guimaraeset al., 2009)." (PMID 33211060, 2020). "One of the key central nodes in the top DEGs in Myd88−/− mice at both 25 and 47 weeks post-infection was guanylate-binding protein 2 (Gbp2), which is considered a potential marker for esophageal squamous cell carcinoma." (PMID 28201999, 2017). "GBP2 is highly expressed in esophageal SCC, where it represents a potential biomarker." (PMID 35436989, 2022). "The expression of GBP2 in esophageal squamous cell carcinoma (SCC) is significantly higher than that in adjacent normal epithelium, and may be used as an important biomarker for esophageal SCC." (PMID 34026364, 2021). "However, high expression of GBP2 is an indicator of esophageal squamous cell carcinoma (ESCC)." (PMID 35436989, 2022).
pancreatic adenocarcinoma (5 papers, 2021 to 2025). "In pancreatic adenocarcinoma, however, high GBP2 forecasts poor survival, tied to immune evasion and acidosis adaptation, quantifiable through RNA sequencing, tissue proteomics, or tumor microenvironment analysis." (PMID 40564939, 2025). "It was reported that the overexpression of GBP2 was correlated with an advanced T classification and poor OS in pancreatic adenocarcinoma." (PMID 35356208, 2022).
Alzheimer disease (4 papers, 2021 to 2025). A progressive, neurodegenerative disease characterized by loss of function and death of nerve cells in several areas of the brain leading to loss of cognitive function such as memory and language. "Therefore, we speculated that the GBP2 gene may be a causative factor in inducing neuroinflammation in neurodegenerative diseases like Alzheimer’s disease and confirmed the expression of GBP2 in Alzheimer’s disease animal models." (PMID 38791092, 2024). "There are reports that GBP2 is highly expressed in representative brain disorders such as Alzheimer’s disease." (PMID 38791092, 2024). "To investigate whether GBP2 is highly expressed in an actual neurodegenerative disease like Alzheimer’s disease, we examined the expression of GBP2 in an Alzheimer’s disease mouse model." (PMID 38791092, 2024). "Interestingly, FTD-Tau patients and late stage Alzheimer’s Disease patients, upregulation of several A1-specific genes (e.g., GBP2, SERPING1, FKBP5) was observed." (PMID 34158119, 2021). "To more quantitatively investigate whether inflammatory reactive astrocytes are specifically adjacent to inflamed vessels, we probed tissue sections from an Alzheimer’s disease (AD) cohort and asymptomatic age-matched controls for GFAP, GBP2, and VCAM-1 expression." (PMID 36323693, 2022).
dengue (4 papers, 2021 to 2025). "GBP2 was also part of a 20-gene set that was strongly associated with the progression to severe dengue." (PMID 36595532, 2023). "However, in severe cases, GBP2 levels decline during the defervescence phase, likely due to heightened oxidative stress, and this decrease correlates with increased plasma leakage—a hallmark of severe dengue." (PMID 41181145, 2025). "Notably, GBP2 expression is associated with dengue disease severity." (PMID 41181145, 2025). "Thus, GBP2 plasma levels, alongside clinical symptoms, may serve as a biomarker for dengue severity." (PMID 41181145, 2025). "Of interest, we observed that several predictive genes of severe dengue, including GYG1, TOR3A, SPON2, GRAP2 and GBP2, were also highly transcribed in the ASCs and effector T cells at Day −1 in our dataset." (PMID 35345453, 2022).
lupus nephritis (4 papers, 2022 to 2026). Glomerulonephritis in the context of systemic lupus erythematosus. "GBP2 has been implicated in several rheumatoid diseases, including rheumatoid arthritis, lupus erythematosus, lupus nephritis, and primary Sjögren’s syndrome." (PMID 41181145, 2025). "Regarding lupus nephritis, GBP2 expression is significantly upregulated in renal tissues compared to healthy controls." (PMID 41181145, 2025).
schizophrenia (4 papers, 2017 to 2024). A major psychotic disorder characterized by abnormalities in the perception or expression of reality. "The findings of the document suggest that GBP2 gene may potentially play a role in immune function related to the etiology of schizophrenia, which may impact risk assessment, prevention, and treatment strategies." (PMID 39286150, 2024). "Guanylate-binding protein 2 (GBP2) is another gene that was replicated and upregulated in five studies assessing gene expression in schizophrenia." (PMID 39845204, 2024). "The paralogous genes of GBP1, MT2A and APOL1, including GBP2, MT1G, MT1E, MT1F, MT1L and APOLD1, were also upregulated in the schizophrenia cases." (PMID 28809853, 2017).
brain injury (3 papers, 2020 to 2023). Acute and chronic (see also brain INJURIES, CHRONIC) injuries to the brain, including the cerebral hemispheres, CEREBELLUM, and brain STEM. "GBP2 is also associated with apoptosis, and the upregulation of GBP2 is associated with neuronal apoptosis in the rat brain cortex following traumatic brain injury." (PMID 33986754, 2021).
colon cancer (3 papers, 2012 to 2022). "Similarly to our results, a previous study demonstrated that GBP2 might be involved in the progression of colon cancer." (PMID 32812032, 2020). "Therefore, the treatment of colon cancer with CPT11 is potentially regulated by LIGP1, GM12250 and GBP2, and exerts anti-cancer effects through mediating the NOD-like signaling pathway." (PMID 32812032, 2020).
COVID-19 (3 papers, 2022 to 2024). A disease caused by infection with severe acute respiratory syndrome coronavirus 2. "Our findings revealed a causal impact of CD4+ TEM cell markers on the risk of PTB and COVID-19, providing evidence identifying two markers (GBP2 and LAG3) as prospective targets for the prevention of PTB and COVID-19 infection." (PMID 39337460, 2024). "Upregulated genes in early COVID-19 mortality included many involved with interferon signaling (e.g., GBP2, ISG15), the NF-κB pathway (e.g., NFKB2, NFKBIA), and TNF-α and IL-1 signaling (e.g., TANK, NOD1, RELA)." (PMID 35446789, 2022). "We focused on the significant causality of GBP2 and LAG3 for PTB and COVID-19, respectively." (PMID 39337460, 2024). "Based on CellChat analyses, monocytes communicated predominantly with CD4+ TEM cells positively expressing PTB markers (GBP2, TRAV1-2, and ODF2L) and COVID-19 markers (LAG3 and SLFN5) in both PTB and COVID-19." (PMID 39337460, 2024). "Genes that were found to be upregulated in the early COVID-19 mortality cases and involved with the interferon (ISG20, IRF1, GBP2) and NF-κB (NFKB2, NFKBIA, TNFAIP3) pathways showed linear decline with longer symptomatic interval." (PMID 35446789, 2022). "However, there were no significant results to indicate that GBP2, TRAV1-2, and ODF2L can be used as factors to estimate the incidence of COVID-19." (PMID 39337460, 2024).
HIV-1 infection (3 papers, 2020 to 2023). The type species of lentivirus and the etiologic agent of acquired immunodeficiency syndrome (AIDS). "For example, HIV-1 infection activates LTR12C elements upstream of the interferon-inducible genes GBP2 and GBP5 that encode for broad-spectrum antiviral factors." (PMID 33021676, 2020). "In line with this, HIV-1 infection triggered the expression of a unique GBP2 transcript variant by activating a cryptic transcription start site within LTR12C." (PMID 33021676, 2020). "Combining an unbiased RNA-sequencing approach with mechanistic analyses, we demonstrate that these solo-LTRs harbor transcription start sites that are activated upon HIV-1 infection and govern the expression of GBP2 and GBP5." (PMID 33021676, 2020). "We would also like to point out that HIV-1 infection resulted in a more pronounced activation of the LTR12C repeat upstream of GBP2 (∼8-fold increase) in comparison to the LTR12C element upstream of GBP5 (∼2-fold increase), and only the former reached statistical significance." (PMID 33021676, 2020). "Although knockout of specific LTR12C elements is challenging due to their repetitive nature, this experimental approach would also allow to investigate whether the induction of LTR12C-driven GBP2/5 expression upon HIV-1 infection has a significant effect on viral replication." (PMID 33021676, 2020). "HIV-1 infection results in the upregulation of several LTR12C elements, which act as promoters for the interferon-inducible guanylate-binding proteins 2 (GBP2) and 5 (GBP5)." (PMID 35891571, 2022). "Similarly, GBP2 and GBP5 are two guanylate binding proteins known to restrict HIV-1 entry and previously shown to be transcribed from LTR12C elements upon HIV-1 infection of primary CD4+ T cells." (PMID 38168352, 2023). "Notably, HIV-1 infection induced the expression of IFN-γ in our RNA-seq study, suggesting that HIV-1 may at least in part activate LTR12C-driven GBP2 and GBP5 expression via an increased release of IFN-γ." (PMID 33021676, 2020).
nonalcoholic fatty liver disease (3 papers, 2023 to 2025). "GBP2 has been implicated in the pathogenesis of various metabolic disorders, including nonalcoholic fatty liver disease and diabetic complications." (PMID 41181145, 2025). "In the context of nonalcoholic fatty liver disease, GBP2 expression is significantly elevated compared to normal hepatic tissues and contributes to hepatic lipid accumulation through the PPARγ–CD36 axis." (PMID 41181145, 2025). "According to the existing research, GBP1 was repressed in hepatitis B virus‐infected patients, GBP2 expression levels were enhanced in patients with nonalcoholic fatty liver disease, and overexpression of GBP5 could induce liver injury and inflammation." (PMID 37551111, 2023).
parasitic infection (3 papers, 2021 to 2025). "Our RIP-seq results revealed that GBP2 bound to mRNAs encoding proteins that are essential for asexual development; however, the parasitemia course was comparable in mice infected with Δgbp2 versus control parasites." (PMID 34604117, 2021). "Guanylate-binding protein 2 (GBP2) is an interferon-inducible GTPase that plays a critical role in innate immunity by defending against viral, bacterial, and parasitic infections through mechanisms such as furin inhibition and inflammasome activation." (PMID 41181145, 2025).
prion disease (3 papers, 2019 to 2024). A transmissible disease that is caused by a protein that is able to induce abnormal folding of normal cellular proteins, leading to characteristic spongiform brain changes, which are associated with neuronal loss without an inflammatory response. "To assess, if formation of A1-astrocytes also plays a role in human prion diseases, we stained human brain tissue sections for the putative A1-astrocyte markers C3 and guanine-binding protein 2 (GBP2)." (PMID 31118110, 2019). "Numerous inflammatory (C3+ or GBP2+) astrocytes can be found in tissues of both murine prion disease and human CJD cases, and expression of C3 and GBP2 is significantly upregulated in CJD brain tissue and is associated with disease duration and risk genotype." (PMID 34539348, 2021). "In human samples of sporadic Creutzfeldt–Jakob disease, a prion disease previously known as transmissible spongiform encephalopathy, reactivity to GBP2 but not to C3 has been found, thus indicating that GBP2 is a better marker for A1 astrocytes at least for this disease." (PMID 38891053, 2024).